TPT1 (tumor protein, translationally-controlled 1)
Description:
Involved in calcium binding and microtubule stabilization. Acts as a negative regulator of TSC22D1-mediated apoptosis, via interaction with and destabilization of TSC22D1 protein.
Synonyms: TCTP; HRF; fortilin; p02; p23
Tractability: PROTAC: ubiquitination databases record sites on it; its protein half-life has been measured.
Gene: Protein-coding gene on chromosome 13 (45,333,471 to 45,341,284, reverse strand). Ensembl gene ENSG00000133112.
Subcellular location: Cytoplasm
Subcellular location (Human Protein Atlas): Cytosol
Gene Ontology:
Molecular function: calcium ion binding; protein binding; RNA binding
Biological process: negative regulation of intrinsic apoptotic signaling pathway in response to DNA damage; response to virus; calcium ion transport; intracellular calcium ion homeostasis; negative regulation of apoptotic process; negative regulation of apoptotic signaling pathway; negative regulation of autophagy; regulation of apoptotic process
Cellular component: cytoplasm; cytoplasmic microtubule; cytosol; extracellular exosome; extracellular region; multivesicular body; nucleus; spindle pole
Genetic constraint (gnomAD): Loss-of-function variants: 5 observed, 20.2 expected, observed/expected ratio (o/e) 0.25, 90% interval 0.13 to 0.52. The upper end of that interval is the gene's LOEUF score, 0.52, which puts it in group 2 of 6, group 1 being the genes least tolerant of losing a copy. Missense variants: 130 observed, 215.3 expected, observed/expected ratio (o/e) 0.6, 90% interval 0.52 to 0.7. Synonymous variants: 89 observed, 74.64 expected, observed/expected ratio (o/e) 1.19, 90% interval 1 to 1.42.
Homologues: Orthologues: chimpanzee TPT1 (100% identical), dog TPT1 (100% identical), macaque TPT1 (100% identical), pig TPT1 (100% identical), zebrafish tpt1 (67% identical), tropical clawed frog tpt1 (66% identical), Drosophila melanogaster Tctp (49% identical), Caenorhabditis elegans tct-1 (38% identical).
Diseases named in the same sentence as TPT1 in open-access papers:
TPT1 is named in the same sentence as 105 diseases in open-access papers, as found by Europe PMC text mining. Sharing a sentence is not in itself a finding about the gene and the disease. The quoted sentences say what the papers report.
breast carcinoma (24 papers, 2011 to 2025). "Such as CMSS1 and ZHX2 in uterine cancer, OSBPL8, FAM214A in breast cancer, TPT1, GPRIN3, and VAV3 in pancreatic cancer." (PMID 37024957, 2023). "It was found to be upregulated in various cancers, including breast cancer, pancreatic cancer, HCC and EOC; furthermore, the high expression of TPT1 was significantly associated with the malignant behaviour of the tumour and the prognosis of the patient." (PMID 33428595, 2021). "The TPT1 gene was identified as the most differentially downregulated in revertant human leukemia cell U937 and breast cancer cells such as MCF7, compared with their malignant counterparts." (PMID 34589516, 2021). "Interestingly, TPT1/TCTP protein is known to act as anti apoptotic protein in cancer cells and is highly expressed in various cancers including breast cancer." (PMID 25268751, 2014). "Low expressions of TPT1/TCTP and SETDB1 are correlated in leading to a better prognosis of breast cancer and colon cancer patients, respectively, which supports clinical benefits of the IO relationship normalization." (PMID 37269056, 2023). "Inhibition of TPT1 by binding an anti-malaria drug, Dihydroartemisinin (DHA), to its phosphorylated form in breast cancer cell lines reduced cell growth and induced apoptosis." (PMID 34589516, 2021). "It is suggested that elevated expression of TPT1, PLIN2 and FABP3 might play a role in suppressing goat mammary tumor formation." (PMID 30009039, 2018).
colorectal cancer (12 papers, 2012 to 2024). A primary or metastatic malignant neoplasm that affects the colon or rectum. "Recently, considerable attention has focused on miR-455-3p in malignant tumors; miR-455-3p expression was downregulated in colorectal cancer, while cell proliferation was inhibited by attenuating TPT1 expression." (PMID 37400847, 2023).
lung carcinoma (12 papers, 2012 to 2024). "TPT1 was predicted as the candidate target of miR-216a-5p, which has been reported to contribute to tumor progression such as hepatocellular carcinoma, lung cancer and prostate cancer." (PMID 32792860, 2020).
pancreatic cancer (11 papers, 2015 to 2024). "In pancreatic cancer, this miRNA functions in a tumor-suppressive way by targeting translationally controlled tumor protein (TPT1), and levels of this miRNA are significantly associated with large tumor size and advanced TNM stage." (PMID 32258065, 2020). "For example, miR-216b-5p as a tumor-inhibiting factor to hinder proliferation by targeting TPT1 in pancreatic cancer cells." (PMID 31920462, 2020). "MiR-216a is involved in the progression of pancreatic cancer through the two-axis, including miR-216a/tetraspanin-1 (TSPAN1)/integrin alpha-2 precursor (ITGA2) and LINC01133/miR-216a-5p/translationally-controlled tumor protein (TPT1)." (PMID 38559560, 2024).
melanoma (9 papers, 2012 to 2025). A malignant, usually aggressive tumor composed of atypical, neoplastic melanocytes. "The TPT1 expression was correlated with poor survival and CTL score in various melanoma patients." (PMID 35440620, 2022).
prostate carcinoma (8 papers, 2013 to 2025). A carcinoma that arises from epithelial cells of the prostate gland. "TPT1 is a long non-coding RNA that is dysregulated in prostate cancer." (PMID 41347211, 2025).
colon cancer (7 papers, 2012 to 2024). "Recently, it has been shown that TPT1 transcripts were highly expressed and enriched in all EV subtypes from the human colon cancer LIM1863 cell line, thus speculating that it could be translated upon EV uptake in recipient cells." (PMID 37842235, 2023).
glioblastoma (6 papers, 2014 to 2024). The most malignant astrocytic tumor (WHO grade IV). "Previous research has shown that miR-489-3p was sponged by LINC01446 and targeted TPT1 to regulate glioblastoma progression." (PMID 33193658, 2020). "LINC01446 promoted the progression of glioblastoma cells by modulating miR-489-3p/TPT1 axis." (PMID 32717723, 2020). "LINC01446 promotes glioblastoma progression by modulating the miR-489-3p/TPT1 pathway." (PMID 31890219, 2019).
glioma (6 papers, 2009 to 2024). A benign or malignant brain and spinal cord tumor that arises from glial cells (astrocytes, oligodendrocytes, ependymal cells). "We identified several targets involved in glioma growth and migration, specifically CXCL1, CD81, TPT1, Gas6 and AXL proteins." (PMID 19558675, 2009).
breast tumors (4 papers, 2014 to 2024). "Recently it was also reported that high-TPT1 status associates with poorly differentiated, aggressive grade breast tumors, predicting poor prognosis." (PMID 25268751, 2014). "The Cancer Genome Atlas Breast Invasive Carcinoma (TCGA-BRCA) or Molecular Taxonomy of Breast Cancer International Consortium (METABRIC) databases showed a higher expression of TPT1/TCTP in normal breast tissues than in primary breast tumors." (PMID 37842235, 2023).
cervical cancer (3 papers, 2014 to 2025). A primary or metastatic malignant neoplasm involving the cervix. "Despite the ample evidence and discussion of the association between TPT1 overexpression and cancer, it is rarely studied in cervical cancer." (PMID 34589516, 2021). "Gene sets, pathways, and functional protein interactions associated with TPT1 were identified using the TCGA data cohort of cervical cancer." (PMID 34589516, 2021). "The dual function of TPT1 in defense against infection and promoting cell survival, two events deterministic for the cellular fate in cervical cancer, underlines its importance in cervical cancer development." (PMID 34589516, 2021). "The causative relationships between these pathways with TPT1 overexpression in cervical cancer warrant verification." (PMID 34589516, 2021). "In alignment with it, the TPT1 gene transciption was remarkably upregulated in cervical cancer cell lines (increased by 125% in SiHa cells and 111% in HeLa cells, compared to HCerEpic cells)." (PMID 34589516, 2021). "In conclusion, we demonstrate a positive correlation between TPT1 expression and cervical cancer progression." (PMID 34589516, 2021). "These genes are implicated in the metabolic reprogramming, cell proliferation, transforming activity, and invasion of cervical cancer, potentially in concert with TPT1 activity." (PMID 34589516, 2021). "The data of TPT1 gene transcription in cervical cancer tissues were downloaded from the TCGA database and analyzed by GSEA to identify gene sets and pathways associated with differential TPT1 expression." (PMID 34589516, 2021). "To get more insights into the trajectory of TPT1 expression in cervical cancer evolvement, we compared TPT1 protein levels in cervix tissues from age-matched patients with cervicitis, CINIII, and cervical cancer, by immunohistochemical staining (IHC)." (PMID 34589516, 2021). "While no clinical evidence is available, a few works have used human papillomavirus (HPV)-infected cervical cancer cell lines to examine the role of TPT1 in cell survival." (PMID 34589516, 2021). "There is increasing evidence that indicates the involvement of translationally controlled tumor protein 1 (TPT1) overexpression in cancer development, but little is known about its implication in cervical cancer." (PMID 34589516, 2021). "In particular, evaluation of the significance of TPT1 delivered via circulation would hugely benefit cervical cancer diagnosis." (PMID 34589516, 2021). "We collected cervical cancer tissues from the local hospital to characterize the status of TPT1 expression." (PMID 34589516, 2021). "TPT1 protein expression was also significantly higher in both human cervical carcinoma SiHa and HeLa cells than in the human normal cervical epithelial cell line HCerEpic." (PMID 34589516, 2021). "Our results, for the first time, demonstrate a strong correlation of upregulated TPT1 expression with cervical cancer progression, suggesting that TPT1 might provide a potential biomarker for cervical cancer progression." (PMID 34589516, 2021). "The multiplicity of TPT1 function in the pathway network, evident in most common cancers and tentatively inferred by our data, offers a great impetus to investigate its therapeutic potential in cervical cancer management." (PMID 34589516, 2021). "In the present study, by analyzing both tissue and serum TPT1 levels from clinical subjects and online databases, we attempt to clarify the relevance of TPT1 to cervical cancer development and the potential value of serum TPT1 as a facile indicator of cancer diagnosis and prognosis." (PMID 34589516, 2021). "Although we could not clarify whether the increased TPT1 was a phenotype secondary to other alterations in cervical cancer, it is plausible to speculate that TPT1 was proactively involved in the examined pathways." (PMID 34589516, 2021). "Regardless of the small sample size, it might imply a predominance of post-transcriptional tuning of TPT1 in the cervical cancer niche." (PMID 34589516, 2021).
cervical cancer (continued). "Serum level of TPT1 was also increased in cervical cancer patients compared to healthy subjects." (PMID 34589516, 2021). "Monitoring the alteration of the TPT1 protein at the systemic level in cervical cancer is especially meaningful as it could considerably alleviate the diagnostic burden and may serve as a convenient biomarker to assist early detection of cancer or treatment evaluation." (PMID 34589516, 2021). "Three merits of bringing TPT1 onboard in the battle against cervical cancer are in sight—opening an earlier window for cervical cancer intervention, circumvention of the obstacle of tissue sampling, and a prompt establishment of a tractable therapy option using current anti-TPT1 drugs." (PMID 34589516, 2021). "However, hampered by the inherent difficulties of research resources, our knowledge of the association between TPT1 and human cervical carcinoma is largely absent." (PMID 34589516, 2021). "We assessed the levels of TPT1 in surgical tissue and sera of patients with cervicitis, cervical intraepithelial neoplasia III, and cervical cancer, as well as in normal and cancerous cervical cell lines." (PMID 34589516, 2021). "TPT1 expression in circulation was also determined in CINIII and cervical cancer patients, with sera from age-matched healthy women as the normal control." (PMID 34589516, 2021). "We next sought an understanding of how the TPT1 protein is functionally involved in pathways of apoptosis, proliferation, and EMT, the most frequently dysregulated pathways during cervical cancer development." (PMID 34589516, 2021). "A continuous increase in the TPT1 positive rate was observed in the order of control (6.7%), cervicitis (27%), CINIII (46%), and cervical cancer (69%)." (PMID 34589516, 2021). "We found that the TPT1 expression was significantly increased in cervical cancer tissue compared to all nonmalignant cervical tissues, including samples of cervicitis, cervical intraepithelial neoplasia III, and normal controls." (PMID 34589516, 2021). "In another study using a mouse cervical cancer model inoculated with HeLa cells, TPT1 protein expression increased in the advanced tumor but not in the stage of tumor initiation." (PMID 34589516, 2021). "Unlike the cervical cancer cell lines, where a dramatic upregulation of TPT1 at both mRNA and protein levels was detected, the relative TPT1 gene transcription in about half of the cancerous tissue samples did not distinguish themselves from their paracancerous controls." (PMID 34589516, 2021).
myocardial infarction (3 papers, 2011 to 2022). Gross necrosis of the myocardium, as a result of interruption of the blood supply to the area, as in coronary thrombosis. "Hprt, Rpl13a and Tpt1 are a set of stably expressed reference genes for accurate gene expression normalization in myocardial infarction studies in mice." (PMID 21858224, 2011). "Using the geNorm algorithm, we were able to identify a set of three reference genes, Hprt, Rpl13a and Tpt1, which can be used for accurate gene expression normalization in qPCR experiments on mouse myocardial infarction tissue." (PMID 21858224, 2011).
ovarian carcinoma (3 papers, 2014 to 2021). A malignant neoplasm originating from the surface ovarian epithelium. "Most metastatic‐related proteins (eg, coronin‐1A, TPT‐1, VASP, HSP90α, cofilin, and Arp 2/3) were identified in both CAB and CAO patients, suggesting their association with organotropism of metastatic breast and ovarian cancers." (PMID 32123828, 2019).
type 2 diabetes (3 papers, 2018 to 2022). "Also, Tpt1, which is highly expressed in skeletal muscle, is associated with type 2 diabetes." (PMID 29910734, 2018). "TPT1 regulates glucose metabolism and has been investigated as a drug target for type 2 diabetes." (PMID 36276976, 2022).
COVID-19 (2 papers, 2021 to 2023). A disease caused by infection with severe acute respiratory syndrome coronavirus 2. "Based on recent publications, TPT1 plays an important role in the development of COVID-19, and it can be used to predict COVID-19." (PMID 37007947, 2023).
cerebral palsy (1 paper, 2025). A group of disorders affecting the development of movement and posture, often accompanied by disturbances of sensation, perception, cognition, and behavior. "A study suggested that diminution of TPT1 up-regulates miR-200a to improve neurobehavior and oxidative stress injury in cerebral palsy rats." (PMID 40417115, 2025).
cervicitis (1 paper, 2021). An acute or chronic inflammatory process that affects the cervix. "We also sought to address the differential expression of TPT1 in noncancerous cervical lesions including cervicitis and pre-cancerous CINIII neoplasia." (PMID 34589516, 2021).
folic acid deficiency (1 paper, 2020). "Tpt1 is a gene implicated in the cellular DNA damage response, known to be upregulated in the context of folic acid deficiency and homocysteine elevation (and amyloid itself)." (PMID 32943069, 2020).
Insulin resistance (1 paper, 2024). Increased resistance towards insulin, that is, diminished effectiveness of insulin in reducing blood glucose levels.
liver disease (1 paper, 2025). "This implies that TPT1 may serve as a marker or potential target for assessing LSECs state in the context of liver disease." (PMID 40723338, 2025).
type 1 diabetes (1 paper, 2024). "This confirms the correlation between TPT1 and NBN and T2DM, but not with type 1 diabetes." (PMID 39459569, 2024).